GPX4 (glutathione peroxidase 4)
Diseases named in the same sentence as GPX4 in open-access papers (continued):
Sharing a sentence is not in itself a finding about the gene and the disease.
cancer (continued). "Remarkably, UA enhances susceptibility to ferroptosis by impeding the SLC7A11/GSH/GPX4 Axis and suppressing the fatty acid desaturase FADS2, suggesting promising prospects for UA's clinical utility in cancer treatment." (PMID 40535804, 2025). "Inhibition of DHODH significantly induced mitochondrial lipid peroxidation and ferroptosis in cancer cells with low GPX4 expression, but only made cancer cells with high GPX4 expression sensitive to ferroptosis." (PMID 41293165, 2025). "The GPX4‐dependent surveillance system serves as the main monitoring and regulatory mechanism for ferroptosis in cancer cells." (PMID 39297393, 2025). "System xCT inhibitors synergize with anti‐PD1 therapy by reversing T cell exhaustion in “cold” tumors, whereas GPX4 degraders eliminate apoptosis‐resistant mesenchymal cancer stem cells." (PMID 40919133, 2025). "SLC7A11 inhibition, cysteine deprivation, or targeting GPX4 have been reported to effectively enhance lipid peroxidation and induce ferroptosis in several cancer types." (PMID 40464376, 2025). "The strategy in which Cu2+ and erastin induce autophagy‐mediated degradation of GPX4—thereby reversing cancer cell resistance to ferroptosis—reveals a novel anticancer modality." (PMID 41323827, 2025). "Studies have demonstrated that FSP1 acts synergistically with GPX4 and glutathione to inhibit ferroptosis in cancer cells, thereby promoting cancer progression." (PMID 40822852, 2025). "This strategy holds great promise for clinical application, given the development and deployment of multiple small molecules to inactivate GPX4 in the context of cancer treatment." (PMID 40485847, 2025). "Through proteinomics, we identified an interesting protein—HSPA5, which was reported to stabilize GPX4 and inhibit ferroptosis in cancers." (PMID 40603306, 2025). "Subsequently, we investigated the correlation between GPX4 expression and survival outcomes across a range of cancer types." (PMID 41142608, 2025). "Recent studies have also demonstrated that abnormal expression of GPX4 was related to cancer initiation and progression." (PMID 40746894, 2025). "Taken together, our results provide novel insights into how GPX4 promotes cancer progression in COAD and suggest its potential as a biomarker for predicting prognosis." (PMID 40746894, 2025). "Targeting DHODH can therefore selectively eliminate cancer cells that are otherwise refractory to apoptosis or necroptosis, while sparing normal cells that rely more heavily on salvage pathways and cytosolic GPX4 for redox protection." (PMID 41369379, 2025). "Previous research has proved that mesenchymal-high cancers behave intensive sensibility to ferroptosis inducers, particularly GPX4 inhibitors." (PMID 39881868, 2024). "Wan Seok Yang's 2014 paper in Cell, “Regulation of ferroptotic cancer cell death by GPX4,” discusses ferroptosis's relevance in cancer research." (PMID 38312575, 2024). "For instance, combining GPX4 inhibitors with agents that increase ROS levels or inhibit other antioxidant pathways can potentiate ferroptosis and enhance cancer cell killing." (PMID 39239068, 2024). "This was further reinforced by our prior study, which demonstrated that ICG in tandem with NIR encourages cancer cell ferroptosis through the down-regulation of GPX4 and SLC7A11." (PMID 38399278, 2024). "Reduced cholesterol accumulation in cancer cells induces lipid oxidative stress through the reduction of glutathione peroxidase 4 (GPx4) leading to ferroptosis." (PMID 38263873, 2024). "Evidently, this does not only apply to in vivo studies using tissue-specific ablation of GPX4, but also to other ferroptosis-related disease models, such as tissue ischemia/reperfusion injury, intoxication, neurodegeneration and cancer." (PMID 38908072, 2024). "Pharmacological therapies targeting GPX4 are a promising strategy for inducing ferroptosis in cancer cells, including clear-cell carcinomas that resistant to conventional treatments." (PMID 39090114, 2024).
cancer (continued). "As the inducers of ferroptosis, RSL3 and erastin have been proved to inhibit the system Xc-/GSH/GPX4 pathway, which provides novel ideas for treating drug-resistant cancer cells." (PMID 38711989, 2024). "The toxicity observed in embryos underscores the critical role of GPx4 in embryonic cells, akin to undifferentiated cancer cells, which are prevalent in advanced cancer." (PMID 39594547, 2024). "Second, elucidating the circumstances under which cancer cells utilize GPX4-dependent or GPX4-independent antioxidant pathways, including those involving 7-DHC, to evade ferroptosis is crucial." (PMID 38523816, 2024). "Among those mechanisms, GPX4, a critical enzyme involved in cellular defense against oxidative damage, represents a promising target for eliminating cancer cells through ferroptosis." (PMID 39664583, 2024). "Given that therapy-resistant cancer cells are particularly vulnerable to GPX4-targeted treatments, the potential of ferroptosis-inducing agents to enhance existing cancer therapies is promising." (PMID 38962561, 2024). "Here, we demonstrate that the addition of selenium increases the activity of GPx4 in cancer cells, which leads to the reversal of lipid peroxidation seen with P-AscH− treatment." (PMID 38539894, 2024). "Functionally, loss of Treg cells secondary to Gpx4 ablation potentiated antitumor activity, establishing a critical role for Gpx4 in protecting intratumoral Treg and offering a novel therapeutic strategy to improve anti-cancer treatments." (PMID 39007133, 2024). "The chemical and molecular mechanisms of antioxidant enzymes, enzyme-related diseases (cancer, cardiovascular, lung, metabolic, and neurological diseases), and the role of enzymes (e.g., GPx4) in cellular processes such as ferroptosis are discussed." (PMID 38483584, 2024). "Overall, the system xc−/GSH/GPX4 pathway connects ferroptosis, lipid metabolism, and iron metabolism and suggests a potential target for ferroptosis-inducing cancer therapies." (PMID 39188677, 2024). "Dihydroorotate dehydrogenase (DHODH) inactivation triggers significant mitochondrial lipid peroxidation and ferroptosis in cancer cells with low expression of glutathione peroxidase 4 (GPX4low)." (PMID 38534454, 2024). "The research results show that targeting GPX4 directly can induce cancer cells' ferroptosis more effectively." (PMID 38333875, 2024). "For instance, low expression of ferroptosis defense genes like FSP1, DHODH, or GPX4 can make cancer cells highly dependent on the remaining defense arm, providing potential targets for inducing ferroptosis in specific cancer types." (PMID 38562143, 2024). "Pharmacological inhibition (e.g., by RSL3 or ML162 treatment) or the genetic ablation of GPX4 induces ferroptosis in a multitude of cancer cell lines." (PMID 38428031, 2024). "Chemotherapy-resistant cancer cells with heightened iron dependency exhibit vulnerability to ferroptosis upon GPX4 inhibition, providing a promising therapy for effective cancer treatment." (PMID 38339263, 2024). "For instance, commonly used inducers like RSL3 and Erastin act by directly inhibiting GPX4 and SLC7A11, respectively, but they fail to comprehensively modulate cancer-associated signaling networks." (PMID 39881871, 2024). "A case of previous study has found that mTOR is correlated with GPX4 expression and the interaction between the two can regulate autophagy-dependent cancer cell death." (PMID 38526702, 2024). "It explores the role of the enzyme GPX4 in preventing lipid peroxidation and highlights the potential therapeutic applications of ferroptosis-inducing compounds in cancer treatment." (PMID 38312575, 2024). "Large doses of selenium induce cell death mediated by ferroptosis through abnormal GPx4 and lipid peroxide mechanisms, thereby producing anti-cancer effects." (PMID 39192972, 2024). "Lipid metabolism, particularly involving GPX4 and System Xc- plays a significant role in both the progression of ferroptosis and cancer." (PMID 39015566, 2024).
cancer (continued). "Another study also validated that resistance to different therapies in cancer depended on a high mesenchymal state, which was determined by the inhibitory effect of GPX4 on ferroptosis." (PMID 39061847, 2024). "Our study establishes mitochondria as the key target of CFAs to trigger lipid peroxidation and GPX4 degradation, providing insight into ferroptosis-based cancer therapy." (PMID 39643606, 2024). "Dihydroorotate dehydrogenase (DHODH) is an enzyme situated on the outer surface of the mitochondrial inner membrane, the inactivation of which induces extensive mitochondrial lipid peroxidation and ferroptosis in cancer cells with low GPX4 expression." (PMID 39600338, 2024). "Ferroptosis, a lipid peroxidation-driven cell death program kept in check by glutathione peroxidase 4 and endogenous redox cycles, promises access to novel strategies for treating therapy-resistant cancers." (PMID 38955113, 2024). "In summary, targeting different types of cancer through induction of ferroptosis is a promising therapeutic strategy, and several efforts are currently underway to develop selective GPX4, SLC7A11 and FSP1 inhibitors with enhanced bioavailability." (PMID 38908072, 2024). "The first phase, from 2014 to 2017, highlights keywords like ‘cancer cells, death, injury, 12/15 lipoxygenase, glutamate, gpx4, biomolecules, AD’, focusing on physiological changes and disease effects." (PMID 38962561, 2024). "GPX4 is an essential regulator of ferroptosis in cancer cells as well as a key factor in maintaining cellular redox homeostasis." (PMID 39309443, 2024). "Inhibition of GPX4 in Erlotinib-tolerant persisted cancer cells (erPCC) was also effective in increasing sensitivity to ferroptosis." (PMID 38392321, 2024). "The activation of the PERK-Nrf2-HO-1 signaling pathway led to iron overload, while inhibition of GPX4 further sensitized cancer cells to ferroptosis." (PMID 38780674, 2024). "Subsequent investigations demonstrated that supplementing cancer cells with G3P attenuates ferroptosis induced by GPX4 inhibitors in a GPD2-dependent manner." (PMID 38540171, 2024). "Accumulation of cholesterol in chemoresistant cancer cells, highly enriched in antioxidant molecules such as GPx4, remains unexplained." (PMID 38263873, 2024). "Certain small-molecule agents, including RSL3, ML162, and ML210, can target the nucleophilic active sites of GPX4 to trigger ferroptosis in cancer cells." (PMID 39624080, 2024). "In contrast, lncPVT1 suppresses ferroptosis by downregulating miR-214-3p, which leads to increased GPX4 expression and subsequently promotes cancer progression." (PMID 39763590, 2024). "The development of small molecule covalent inhibitors of GPX4 to effectively target cancer cells is appealing in modern drug development." (PMID 38200609, 2024). "In oncology, GPX4 is recognized for its critical role in mitigating lipid peroxidation and averting ferroptosis, thereby supporting cancer cell survival under therapeutic stress." (PMID 39484165, 2024). "GPX4, a key regulator of ferroptosis in cancer cells, is inactivated by erastin through the depletion of GSH." (PMID 39600338, 2024). "Se nanoparticles also decreased cancer cell viability and proliferation while increasing the mRNA expression of TXN, GPX1, GPX2, GPX3, and GPX4 in many of the cancer cell lines." (PMID 39408290, 2024). "Highly mesenchymal, drug-resistant cancer cells depend on the lipid hydroperoxidase GPX4 to survive." (PMID 39721999, 2024). "Pharmacological inhibition of FSP1 synergized with inhibition of GPX4 to induce ferroptosis in many cancer cells." (PMID 39309443, 2024). "The continued advancement and refinement of GPX4 inhibitors will enrich the repertoire of tools available for exploring ferroptosis induction as a therapeutic strategy in cancer treatment." (PMID 38428031, 2024).
cancer (continued). "Increasing the levels of GPX4 inhibitors has been shown to sharply increase the oxidative sensitivity of drug-resistant cancer cells, and the time period involved is very long." (PMID 38469234, 2024). "In contrast N6F11 represents the first cell type-dependent ferroptosis inducer by selectively degrading GPX4 in cancer cells through the action of TRIM25, exhibiting efficacy and safety simultaneously." (PMID 38844964, 2024). "Several recent studies have illustrated that the mesenchymal state of cancer cells exposes a vulnerability to ferroptosis, a form of metabolic-stress cell death induced by inhibiting the GPX4 lipid peroxidase pathway." (PMID 39419964, 2024). "In this study, some cancer cell lines were unable to induce ferroptosis sufficiently by inhibiting GPX4 and FSP1." (PMID 39273151, 2024). "Ferroptosis, an iron-dependent form of oxidative cell death driven by GSH depletion and GPX4 inactivation, is a promising therapeutic target for cancer, including OS." (PMID 39852136, 2024). "By inhibiting SLC7A11 or GPX4 with ferroptosis inducers (FINs), radioresistant cancer cells and xenograft tumors can be made more sensitive to IR." (PMID 39544291, 2024). "In TCGA database, GPX4's expression in a lot of cancers has changed significantly, and most of them are significantly up-regulated." (PMID 38333875, 2024). "There is a strong relationship between enhanced uptake of cholesterol by chemotherapy resistant cancer cells and the requisite high expression of GPx4 to prevent lipid peroxidation and cell death by ferroptosis." (PMID 38263873, 2024). "An imbalance in ferroptosis defense systems involving GPX4-dependent and GPX4-independent arms creates vulnerabilities in cancer cells." (PMID 38562143, 2024). "While targeting GPX4 holds promise in cancer treatment, a challenge arises from its widespread expression in both cancer and immune cells, which can potentially cause side effects when using traditional GPX4 inhibitors." (PMID 39090114, 2024). "These ncRNAs can target key ferroptosis-related genes such as GPX4, SLC3A2, and SLC7A11, offering novel therapeutic approaches or diagnostic biomarkers for cancer." (PMID 39600338, 2024). "In cancer therapy, promoting ferroptosis of drug-resistant cancer cells by inhibiting GPX4 is seen as a potential therapeutic strategy." (PMID 38957396, 2024). "Although previous studies confirmed the regulation of GPX4 degradation by the proteasome or autophagy pathways, its detailed mechanisms in the ferroptosis of cancer cells, especially in ESCC cells, are unclear." (PMID 38247539, 2024). "If, in cancer, the expression of these ion channels is reduced or dysfunctional, intracellular Ca2+ can be reduced, and GPX4 function is preserved, which counteracts GSH depletion by Cdo1." (PMID 38672271, 2024). "Some chemotherapeutic drugs including apatinib, capsaicin, paclitaxel, etc., trigger ferroptosis via inhibiting GPX4 expression in several cancer cell types." (PMID 38263152, 2024). "Some signaling mechanisms are included in the regulation of GPX4 expression and the modulation of ferroptosis in cancer cells." (PMID 39125992, 2024). "Treatment-resistant mesenchymal-type cancer cells are strongly dependent on GPX4, and lipoxygenase inhibition can block ferroptotic cell death via GPX4 inhibition." (PMID 38424190, 2024). "Combinatorial administration of GPX4 inhibitors and system Xc− inhibitors & cisplatin has been shown to overcome chemotherapy resistance, enhancing the anti-cancer response in various tumors." (PMID 39015566, 2024). "The most well-studied ferroptosis defence systems in cancers include the GPX4-GSH, FSP1-CoQH2, GCH1-BH4 and DHODH-CoQH2 system." (PMID 38472205, 2024). "For example, in response to radiotherapy, cancer cells adapt by enhancing expressions of SLC7A11 or GPX4 to fight ferroptosis induced by radiotherapy." (PMID 38539554, 2024).
cancer (continued). "The paper “Regulation of ferroptotic cancer cell death by GPX4” by Wan Seok Yang exhibited the strongest citation burst (11.37) among these references, with bursts occurring from 2017 to 2019." (PMID 38312575, 2024). "It is worth noting that, among them, linc00857 has been shown to be an oncogenic lncRNA in various cancers, while GPX4 is one of the essential enzymes involved in ferroptosis." (PMID 38561331, 2024). "In short, the inhibition of the GPX4–GSH axis is responsible for the effect of solasoine on cancers." (PMID 39021832, 2024). "This pathway operates independently of Glutathione Peroxidase 4 (GPX4), another primary regulator of ferroptosis, suggesting an alternative method through which SMURF2 can enhance ferroptotic susceptibility in cancer cells." (PMID 39697237, 2024). "Overexpression of GPX4 by cancer cells confers ferroptosis resistance, just as pharmacological upregulation of GPX4 protects healthy tissues." (PMID 38969638, 2024). "The repression of SLC7A11 renders HCC cells susceptible to GPX4 inhibition, while inhibitors of system Xc- or GPX4 selectively eliminate cancer cells but preserve healthy ones." (PMID 38339263, 2024). "The existing body of research acknowledges the critical role of ferroptosis in human cancers, with drug-resistant cancer cells exhibiting increased vulnerability to GPX4 inhibitors in vitro." (PMID 39261475, 2024). "In GC, CircRHOT1 functions to impede ferroptosis in cancer cells by epigenetically governing GPX4 expression." (PMID 39036600, 2024). "This issue arises because ferroptosis inducers such as erastin and RSL3 target solute carrier family 7 member 11 (SLC7A11) and GPX4 - proteins expressed in both normal and cancer cells." (PMID 39534872, 2024). "The antioxidant enzyme GPX4 can directly reduce ROS, thus acting as a central suppressor of ferroptosis in cancer cells." (PMID 38742521, 2024). "By competing with AIFM2 and GPX4, Circ0060467 suppresses cancer cell ferroptosis through its interaction with miR-6805, thereby facilitating HCC progression." (PMID 39036600, 2024). "Collectively, our work demonstrates a viable strategy of A2ARi in combination with inhibition of lipid peroxidation to improve persistence and functionality of ACT against cancer, contributing to the debate over the best way to target GPX4 for cancer therapy." (PMID 38441967, 2024). "Accordingly, genetic or pharmacologic inhibition of SLC7A11 leads to GSH depletion, GPX4 inhibition, and ferroptosis in many types of cancer." (PMID 39624080, 2024). "GSE56315 and TCGA show that GPX4 has good discriminative ability between normal tissue samples and cancer samples (AUC>0.98)." (PMID 38333875, 2024). "GPX4, a key regulator of lipid peroxidation and a central player in ferroptosis, is a potential target for modulating ferroptosis in cancer cells." (PMID 38493165, 2024). "The silencing of GPX4 can enhance the anti-cancer effect of Lapatinib via promoting ferroptosis of NSCLC cells, thereby inhibiting the development of NSCLC." (PMID 38383815, 2024). "Brequinar is a potential agent for treating cancers with low expression of GPX4 (GPX4low) by triggering ferroptosis." (PMID 39595619, 2024). "Inhibition of SLC7A11 inhibits cysteine uptake and reduces GSH synthesis, and GSH depletion results in GPX4 inactivation, ROS accumulation, and ferroptosis in cancer cells." (PMID 38313306, 2024). "Ferroptosis was induced in cancer cells by induction of GPX4 knockout in vitro and mouse xenograft models." (PMID 38738174, 2024). "The pronounced dependence of persistent, drug-resistant malignancies on GPX4 underscores its importance, and its inactivation has the potential to eliminate these cancer cells in vitro and avert tumor recurrence in vivo." (PMID 39090114, 2024). "GPX4 is the only intracellular enzyme that reduces lipid peroxides to lipid alcohols, thus acting as a central inhibitor of ferroptosis in cancer cells." (PMID 39769097, 2024).